CST1 (cystatin SN)
Diseases named in the same sentence as CST1 in open-access papers (continued):
Sharing a sentence is not in itself a finding about the gene and the disease.
COVID-19 (1 paper, 2025). A disease caused by infection with severe acute respiratory syndrome coronavirus 2. "Future studies should include non-COVID-19 GGN cohorts to validate whether CST1 and GIMAP1-GIMAP5 serve as pandemic-unrelated biomarkers or are influenced by COVID-19-associated lung inflammation." (PMID 40535419, 2025).
dry eye (1 paper, 2022). "For instance, LCN1, PIP, LTF, and SG2A1 were substantially reduced in dry eye, while AZGP1, LEG7, CST4, CST1, and ACTB were diminished in MGD." (PMID 35685417, 2022).
eosinophilia (1 paper, 2025). "The results revealed that unlike IFN-γ, IL-4, IL-5, IL-13, ALOX15, CST1, POSTN, and CCL26 were significantly elevated in patients with eosinophilia greater than 5%." (PMID 40978168, 2025). "IL-4, IL-5, IL-13, ALOX15, CST1, POSTN, and CCL26 were significantly elevated in patients who had eosinophilia higher than 5%, but not IFN-γ." (PMID 40978168, 2025).
fungal keratitis (1 paper, 2023). "The downregulation of cystatin-SN has previously been reported in tear fluid samples from patients with fungal keratitis and ocular graft versus host disease." (PMID 37894795, 2023).
fungal ocular infections (1 paper, 2022). "Expression of cystatin SN proteins, an endogenous proteinase inhibitor involved in lipid metabolism and host wound healing responses, was shown to be associated with host stress responses after fungal ocular infections." (PMID 35328532, 2022).
head and neck cancer (1 paper, 2021). A primary or metastatic malignant neoplasm affecting the head and neck. "Indeed, we observed CST1 expression in a subset of fibroblasts from lung, colon, and head and neck cancers with comparable frequencies (1.22–3.61%)." (PMID 34921160, 2021).
laryngeal carcinoma (1 paper, 2022). Carcinoma that arises from the laryngeal epithelium. "Results of biological experiments revealed the inhibitory influence of CST1 deficiency on the proliferative, migrative, and invasive properties of laryngeal cancer cells." (PMID 35498540, 2022). "We designed short hairpin RNAs targeting CST1 for the loss-of-function assays to probe the influences of CST1 in laryngeal cancer cell proliferation and motility." (PMID 35498540, 2022). "We hypothesized that CST1 can promote malignant phenotypes of laryngeal cancer cells and designed loss-of-function assays to explore it." (PMID 35498540, 2022). "After confirming the role of CST1 in laryngeal cancer cells, the lncRNA–miRNA–CST1 interactions were investigated." (PMID 35498540, 2022). "A major shortcoming of this research is lacking animal studies to further support the role of LINC01278/miR-185-5p/CST1 in laryngeal cancer at the preclinical level." (PMID 35498540, 2022). "In conclusion, LINC01278 plays an oncogenic role in laryngeal cancer by suppressing miR-185-5p to enhance CST1 expression, which enriches the molecular mechanism for the carcinogenesis of laryngeal cancer." (PMID 35498540, 2022). "The experimental results demonstrated that CST1 is a tumor facilitator in laryngeal cancer by stimulating cellular proliferative, migrative, and invasive abilities." (PMID 35498540, 2022). "We explored the upstream lncRNA and miRNA for CST1 in laryngeal cancer cells and investigated the functions of these noncoding RNAs, which might offer new insight into the mechanism of laryngeal cancer tumorigenesis." (PMID 35498540, 2022). "CST1 was identified as an upregulated gene in laryngeal cancer tissues based on online data." (PMID 35498540, 2022). "Our experimental findings suggested that CST1 could act as an oncogene to mediate laryngeal cancer carcinogenesis." (PMID 35498540, 2022). "Based on GSE84957, it was found that cystatin SN (CST1) is upregulated in 30 laryngeal cancer specimens compared with the adjacent nonneoplastic tissues by 4.256-fold changes." (PMID 35498540, 2022). "We further demonstrated that miR-185-5p elicits a negative effect on laryngeal cancer proliferation and motility by targeting CST1, suggesting the antioncogenic function of miR-185-5p in laryngeal cancer." (PMID 35498540, 2022).
liver diseases (1 paper, 2023). "The mechanism underpinning the immunoregulatory effect of stem cell transplantation, particularly CST1-based intervention, will shed light on the development of new therapeutic strategies for curing liver diseases or other diseases that involve IFN over-activation." (PMID 36670290, 2023).
metastatic cancer (1 paper, 2023). A carcinoma which has spread from the original site of growth to another anatomic site. "Whole transcriptome sequencing suggested that the expression of CST1 was significantly increased in metastatic cancer, and high CST1 expression was correlated with a worse prognosis." (PMID 36369321, 2023).
papillary thyroid carcinoma (1 paper, 2023). "Ding and colleagues suggested that CST1 regulates papillary thyroid carcinoma cells invasion, migration, and EMT." (PMID 36369321, 2023).
Peri-Implantitis (1 paper, 2023). An inflammatory process with loss of supporting bone in the tissues surrounding functioning DENTAL IMPLANTS. "Similarly, an enhanced expression of CST1 has been observed within peri-implant soft tissues that may influence patients’ susceptibility to peri-implantitis." (PMID 37762137, 2023).
tumor (51 papers, 2010 to 2026). "For instance, CST1, associated with tumor progression, and the fibroblast growth factor 4 (FGF4), imperative for embryonic development, both markedly upregulated in eCAFs and dCAFs, respectively." (PMID 39112478, 2024). "Upregulation of CST1 has been observed in malignant tumours and is associated with cancer cell proliferation, invasion and tumour recurrence." (PMID 35725766, 2022). "The association of CST1 expression with prognosis, gene mutations and tumor immune microenvironment was analyzed using public databases." (PMID 35637432, 2022). "To date, the underlying relationship between CST1 and CatB, and their roles in tumor development, remains poorly understood." (PMID 28383558, 2017). "Little is known about the role of CST1 in cancer, but elevated expression of cystatins is associated with tumor invasion and metastasis." (PMID 24357805, 2013). "Patients with CST1 mutations had significantly worse disease-free survival, suggesting that increased frequency of CST1 mutations may contribute to tumor progression." (PMID 35637432, 2022). "Excitingly, we found a strong association between CST1 and cells in the tumor microenvironment." (PMID 35637432, 2022). "CST1 was positively associated with tumor-associated fibroblasts (CAFs)." (PMID 35637432, 2022). "These suggested that mutations in CST1 may influence tumor progression and, consequently, patients’ outcome." (PMID 35637432, 2022). "Tumor-associated fibroblasts (CAFs) were more abundant in the CST1 high expressed group, whereas endothelial cells, neutrophils, and NK cells were less abundant in the CST1 high expressed group." (PMID 35637432, 2022). "Accordingly, target genes of c-Myc (such as Cst1, Snai2 and Bcl2) related to tumor invasion, metastasis, and drug resistance were upregulated in Panc1 cells with NLS-TLR3 rescue, compared with other two groups." (PMID 40675966, 2025). "In LSCC, miR-375 targets CST1, inhibiting the aggressive phenotype of tumor cells and promoting apoptosis." (PMID 40076805, 2025). "A comprehensive and systemic investigation of the cellular communication among different cell types within GC TME was conducted and demonstrated that iCAFs and CST1+ mCAFs frequently interacted with immune cells and tumor cells, especially the CSCs." (PMID 39950944, 2025). "Here, we aimed to comprehensively define the diagnostic performances of individual and combined detections of serum CST1 with traditional tumor markers (CA125 and HE4) for patients with early EC in a large cohort of 300 serum samples." (PMID 38077439, 2023). "Considering the relatively limited sensitivity of individual detection, we further performed the evaluation of the diagnostic performances of all possible combinations of serum CST1 with traditional tumor markers, CA125 and HE4, for patients with early EC." (PMID 38077439, 2023). "Many studies have concluded that CST1 plays an important role in inflammation, tumorigenesis and tumor metastasis." (PMID 35637432, 2022). "Extending the IHC staining to a total of 154 ESCC patients, we confirmed the prevalence of CST1+ myofibroblasts in the tumor stromal of ESCC patients." (PMID 34921160, 2021). "We identify a tumor-specific subset of CST1+ myofibroblasts with prognostic values and potential biological significance." (PMID 34921160, 2021). "Using orthogonal approaches including immunostaining, CST1+ myofibroblast is confirmed in ESCC tumor stromal, and exhibits prominent prognostic values." (PMID 34921160, 2021). "Although recent studies have also shown that CST1 is a key antigen in humoral immune regulation, there are very few studies on the role of CST1 in the tumour microenvironment." (PMID 33869274, 2021). "Here, the authors characterize the ESCC tumour microenvironment with single-cell RNA-seq, finding CST1 + myofibroblasts with potential biological and prognostic significance as well as immunosuppression signatures." (PMID 34921160, 2021).
tumor (continued). "CST1 staining of tumor and paired normal tissues revealed elevated CST1 expression in CRC tissues compared with that in normal surrounding tissues." (PMID 28300829, 2017). "Albeit increasing evidence showed roles of CST1 in tumor invasion and metastasis, its clinical and prognostic significance in CRC patients has not been well established." (PMID 29383149, 2017). "The chi-square test showed that CST1 expression was significantly correlated with menarche age (p = 0.017), tumor size (p = 0.005), HER-2 status (p = 0.045), and histological grade (p < 0.001)." (PMID 28523467, 2017). "This contradiction suggests that CST1 possibly plays oncogenic or anti-tumor roles in distinct cancers." (PMID 29383149, 2017). "Although MDA-MB-231-mock cells grew steadily, CST1 knockdown MDA-MB-231 cells exhibited significantly suppressed in vivo tumor growth." (PMID 28383558, 2017). "We also demonstrated that CST1-overexpressing cell lines exhibited increased tumor growth as well as metastasis in a xenograft nude mouse model." (PMID 24357805, 2013). "The Hom-MG-1 subgroup highly expressed the innate characteristic genes of microglia (Tmem119, P2ry12, Crybb1, Cst1, Gpr34, and Cx3cr1), poorly expressed tumor activation-related genes, and expressed early activation genes to a certain extent (Jun, Junb, Jund, and Fos)." (PMID 39867913, 2024). "We analyzed the tumor immune microenvironment of CST1 by using the GSE31210 database." (PMID 35637432, 2022). "Taken together, these analyses revealed that CST1 may alter the tumor microenvironment and play a role in suppressing anti-tumor immunity." (PMID 35637432, 2022). "In addition, we observed modest positive correlation between CST1+ fibroblasts and Treg cells in tumor samples." (PMID 34921160, 2021). "CST1+ myofibroblasts are also highly tumor-specific in other cancer types." (PMID 34921160, 2021). "CST1 has also been considered as a potential tumor marker in various epithelial malignancies." (PMID 33828156, 2021). "Moreover, consistent with our data in ESCC, CST1+ fibroblasts were only detected in tumor samples from these cancer types, again confirming their cancer-specificity." (PMID 34921160, 2021). "However, the relationship between CST1 and CatB, and their roles in tumor development are poorly understood." (PMID 28383558, 2017). "Importantly, CST1 knockdown suppressed cancer cell proliferation, soft agar colony growth and tumor growth in a xenograft model." (PMID 28383558, 2017). "Immunohistochemistry showed upregulation of CST1 protein in tumor tissues from patients with CRC." (PMID 24357805, 2013). "Triggering ferroptosis by promoting CST1 in GC cells could inhibit tumor growth and metastasis." (PMID 41188993, 2025). "Interestingly, we found a large number of CST superfamily members in the protein network, which suggested that CST1 may play a role in promoting tumor progression in combination with other members of the CST superfamily." (PMID 35637432, 2022). "Therefore, it is relevant to explore whether CST1 can contribute to tumor progression by affecting the tumor microenvironment." (PMID 35637432, 2022). "Therefore, this study also delved into the impact of CST1 on the tumor immune microenvironment." (PMID 35637432, 2022). "Therefore, a decrease in neutrophils abundance due to CST1 may indirectly reduce neutrophils’ tumor inhibition." (PMID 35637432, 2022). "Therefore, whether CST1 promotes tumor metastasis by killing endothelial cells through a similar mechanism deserves further investigation." (PMID 35637432, 2022). "In this study, we investigated whether CST1 expression induces autophagy and tumor cell survival." (PMID 28300829, 2017). "An increased expression of FCGBP, BPIFB, F5, CST1, and CFB and their correlation to epithelial-to-mesenchymal transition (EMT) under clinorotation were detectable as potential tumor suppressor biomarkers." (PMID 37048115, 2023).
tumor (continued). "Immunoblot showed that in tumor grinding cells of HGC-27-Vector/HGC-27-CST1/HGC-27-GPX4#sh, CST1 overexpression increased the expression of the GPX4." (PMID 36369321, 2023). "Both CM presented proteins involved in proliferation of both tumor and non-tumor cells, of which CAPN1, CST1, LAMC2 and RANBP3 stood out in CM3D and GPC6, ILK, MAPK1, MIF and PICALM in CM2D." (PMID 34884877, 2021). "CST1 and NELL2 proteins were significantly overexpressed in tumour tissues compared with adjacent non-tumour tissues." (PMID 33869274, 2021). "Part of them have been documented to be tumor promoter genes of PC, such as GABRP, CEACAM5, CEACAM6 and CST1." (PMID 31706267, 2019). "Cystatin SN (CST1), a known inhibitor of cathepsin B (CatB), has important roles in tumor development." (PMID 28383558, 2017). "These genes included tumor markers (MUC16), genes that control tumor migration (MYL9), metastasis (CEACAM6, VEGFC, CX3CL1, CST1, CCL5, S100A9, IGF1, NOTCH3), cell adhesion (FN1, CEACAM1), and inflammation (TRAF2, NF-κB2 and RelB)." (PMID 26090868, 2015). "Implanted CST1-GFP and CST3-GFP cells (4 weeks) each enhanced tumor growth relative to the control, and we confirmed the higher CST1 and CST3 expression in implanted tumor tissues." (PMID 24357805, 2013). "Restoring its expression or inhibiting antagonist molecules such as CST1 and SLC7A11 could be an effective strategy for suppressing tumor progression." (PMID 40076805, 2025). "Also, CST1 was regulated by LET-7 in colorectal cancer, thereby affecting the proliferation ability of tumor cells." (PMID 35953439, 2022). "Interestingly, we observed increased expression of FCGBP, BPIFB, F5, CST1, and CFB and their correlation to EMT under SMG, rendering them potential tumor suppressor biomarkers." (PMID 36613598, 2022). "CellPhoneDB analysis showed that the number of ligand-receptor interactions engaging CST1+ fibroblasts was generally much higher in tumor than in nonmalignant samples." (PMID 34921160, 2021). "We confirmed that CST1 protein was expressed in a subset (8.31%) of COL1A1+ fibroblasts in tumor samples, but it was barely detectable (0.27%) in nonmalignant samples." (PMID 34921160, 2021). "We performed differential expression analysis between tumor and nonmalignant samples within F_3 cluster and identified CST1 as the top cancer-specific gene (average logFC=3.0)." (PMID 34921160, 2021). "In another 9 nonmalignant/tumor paired ESCC cases, immunohistochemistry (IHC) results validated the prominent CST1 protein expression in the stroma of tumor-associated fibroblasts (11.95%), while it was absent in adjacent nonmalignant esophagus." (PMID 34921160, 2021). "In addition, we generated two predictive nomograms integrating CST1 expression, the level of CEA, tumor grade, tumor depth, and lymph node metastasis to assess the risk score for overall survival (OS) and disease-free survival (DFS) of CRC patients." (PMID 29383149, 2017). "However, exogenous thymidine supplementation failed to rescue proliferation defects upon CST1 knockdown, indicating that CST1-promoted tumor growth is independent of pyrimidine metabolism." (PMID 41881961, 2026). "In addition, the expression of MDA in tumor tissue decreased after overexpression of CST1, while it increased again after the downregulation of GPX4; opposite effects were seen after down-regulation of CST1." (PMID 36369321, 2023). "However, there were not studies about the relationship of CST1 with tumor infiltrating lymphocytes." (PMID 29383149, 2017). "This “non-basal-like non-classical” tumor subset expresses core signatures such as high TMPRSS4, SLC6A14, IFI27, CST1, and STYK1." (PMID 39774001, 2025). "The most notable examples of down-regulated genes were GUCA2B (FC = 187), TMIGD1 (FC = 129) and CA1 (FC = 121), while CST1 and S100A2 (FC = 131/88.7, respectively) were highly expressed in tumours but not in normal tissue." (PMID 30231850, 2018).
tumor (continued). "Using these data, we validated the low presence of CST1+ fibroblasts in nonmalignant samples, increased exhaustive CD8+ T cells, Treg cells, as well as M2-like macrophages in tumor compared with nonmalignant samples." (PMID 34921160, 2021).